ASCL1 (achaete-scute family bHLH transcription factor 1)
Diseases named in the same sentence as ASCL1 in open-access papers (continued):
Sharing a sentence is not in itself a finding about the gene and the disease.
lymph node metastasis (2 papers, 2018 to 2021). "Significant differences were observed between ASCL1 high and low expression groups in variables including staging, lymph node metastasis, nerve invasion and overall survival." (PMID 33191657, 2021). "Besides, glutathione-disulfide reductase (GSR), human leukocyte antigen complex P5 (HCP5), and achaete-scute family bHLH transcription factor 1 (ASCL1) were upregulated in the SCLC patients with lymph node metastasis." (PMID 30364292, 2018). "ASCL1 were highly expressed in 42.5% (105/247) of pure SCLC patients, and a significant difference was found in variables including TNM staging, lymph node metastasis, nerve invasion, as well as OS." (PMID 33191657, 2021). "A significant difference by χ2 test between ASCL1 positive and negative groups were observed separately in TNM staging (P = 0.047), lymph node metastasis (P = 0.017), nerve invasion (P = 0.024) and STAS (P < 0.001)." (PMID 33191657, 2021).
lymphoma (2 papers, 2018 to 2024). A malignant (clonal) proliferation of B- lymphocytes or T- lymphocytes which involves the lymph nodes, bone marrow and/or extranodal sites. "All that is necessary for the practical implementation of our findings in the routine clinical practice are acquiring and employing three antibodies targeting ASCL1, NEUROD1, and POU2F3, in addition to employing CD8 staining—a well-established technique in lymphoma diagnosis." (PMID 38483588, 2024).
malignant glioma (2 papers, 2019 to 2021). A grade III or grade IV glioma arising from the central nervous system. "In our study, ASCL1-induced neuronal reprogramming of human malignant glioma cells resulted in cell cycle exit and blocked their aggressive proliferation." (PMID 31212628, 2019). "We next investigated the roles of ASCL1 in inducing neuronal reprogramming of human malignant glioma cells." (PMID 31212628, 2019). "All these findings suggested that ASCL1 could reprogram human malignant glioma cells into terminally differentiated neurons and resulted in cell cycle arrest." (PMID 31212628, 2019). "Collectively, these data suggested that the exponential growth of human malignant glioma cells could be inhibited by the ASCL1-induced neuronal reprogramming." (PMID 31212628, 2019).
melanoma (2 papers, 2023 to 2025). A malignant, usually aggressive tumor composed of atypical, neoplastic melanocytes. "In order to examine if melanoma cells can be transdifferentiated into neurons, the neuron-specific transcription factors ASCL1, BRN2, MYT1L, and NEUROD1 were ectopically overexpressed in different melanoma cell lines." (PMID 40715046, 2025). "In addition, we analyzed the enrichment of transcription regulators with the 66 significant enhancers and found that several critical melanoma-associated TFs (e.g., SP1, SNAI2, HEXIM1, ASCL1) preferentially bind at these enhancer loci." (PMID 37904237, 2023). "For this purpose, we ectopically overexpressed the neuron-specific transcription factors ASCL1, BRN2, MYT1L, and NEUROD1 in melanoma cells." (PMID 40715046, 2025).
microcephalies (2 papers, 2015 to 2019). "Here we show that Cenpj, also known as CPAP, a microcephaly gene, is a transcriptional target of Ascl1 in the embryonic cerebral cortex." (PMID 25753651, 2015). "It implicates the proneural factor Ascl1 and the microcephaly protein Cenpj in neuronal migration, thus improving our understanding of human microcephalies and microlissencephalies." (PMID 25753651, 2015). "Here we identify the microcephaly protein Cenpj as a target of Ascl1 involved in multiple steps of cortical neurogenesis." (PMID 25753651, 2015).
prostate adenocarcinoma (2 papers, 2024 to 2025). "ASCL1 is a pivotal regulator of neuroendocrine differentiation and is crucial in driving the transition from prostate adenocarcinoma to aggressive NEPC, a treatment-resistant subtype of CRPC." (PMID 40165961, 2025). "Integrating RNA-Seq data, we explored the expression of genes with ASCL1-bound promoters in ASCL1-high and ASCL1-low NEPC, as well as prostate adenocarcinoma (PRAD) in LuCaP PDXs." (PMID 39470735, 2024).
retinoblastoma (2 papers, 2013 to 2019). A malignant tumor that originates in the nuclear layer of the retina. "Meanwhile, if oscillatory gene expression in some undifferentiated cells/RPCs does not stop due to pathological events (e.g., mutations in genes regulating the stability of mRNA and proteins of genes like Notch1, Hes1, Dll1, Ascl1, Neurog2, etc.), these cells may begin retinoblastoma formation." (PMID 31607861, 2019).
small cell carcinoma (2 papers, 2024 to 2025). A neuroendocrine carcinoma composed of small malignant cells which are often said to resemble "oat cells" under the microscope. "DLL3, a downstream effector of ASCL1 and a Notch signaling inhibitor is highly expressed in NEPC and small cell cancers." (PMID 41514539, 2025). "The lack of apparent NE differentiation is supported by the absence of ASCL1, NEUROD1, and POU2F3, which are all transcription factors associated with small cell neuroendocrine carcinomas, including NEPC." (PMID 38667288, 2024).
asthma (1 paper, 2021). "The GM13-up related to interleukin-26 (IL26, PIK3R5, and LRRC2) was much higher expressed in severe individuals while the GM12-down module related to the nervous system (10%, p = 1.77E-04, i.e., TUBB2B, SPOCK1, and ASCL1) was much lower expressed in severe asthma individuals." (PMID 34759961, 2021).
atherosclerosis (1 paper, 2016). A disease characterized by the build-up of fatty material and calcium deposition in the arterial wall resulting in partial or complete occlusion of the arterial lumen. "In addition, we evaluated the potential relationship between HNF1A rs1183910, LEPR rs4420065, GCKR rs1260326, NLRP3 rs12239046, IL1F10 rs6734238, PPP1R3B rs9987289, ASCL1 rs10745954, HNF4A rs1800961 and SALL1 rs10521222 polymorphisms and CV events or subclinical atherosclerosis in RA patients." (PMID 27534721, 2016).
bladder cancer (1 paper, 2012). "In this report we associated, for the first time to our knowledge, ASCL1 gene to bladder cancer." (PMID 23114535, 2012).
bone metastasis (1 paper, 2022). Transfer of a neoplasm from its primary site to bones. "Meanwhile, brain and bone metastasis were less prevalent in patients classified into YAP1 subtype than those with ASCL1 subtype, respectively, and liver metastasis was decreased in YAP1 subtype than NEUROD1 subtype." (PMID 35311069, 2022).
carcinoid syndrome (1 paper, 2009). "ASCL1 may have a coordinating role in production of serotonin by transcriptional regulation of TPH1 and could thereby be involved in causing the carcinoid syndrome in patients with PET." (PMID 19744316, 2009).
cervical squamous cell carcinoma (1 paper, 2023). A squamous cell carcinoma arising from the cervical epithelium. "Paired ASCL1/LXH8 methylation data on self-collected and clinician-collected samples were available for 485 HPV-positive women (subset A), including one woman with cervical squamous cell carcinoma, 79 women with CIN3, 42 women with CIN2, and 363 controls." (PMID 37100874, 2023).
colorectal tumors (1 paper, 2017). "Methylation of FGF12 has been reported in colorectal tumors but not in matched controls as has methylation of ASCL1." (PMID 28278225, 2017).
congenital central hypoventilation syndrome (1 paper, 2023). "To date, only two genetic variations potentially disrupting ASCL1 have been found (rs533680685 (a 15 bp deletion in the coding region of the gene) and rs267606667 (a missense variant, c.52C > A, p.Pro18Thr)) in patients with congenital central hypoventilation syndrome." (PMID 37958729, 2023).
depressive disorder (1 paper, 2023). A melancholy feeling of sadness and despair. "ASCL1 dysfunction affects the expression of genes associated with the pathogenesis of SZ, as well as bipolar and depressive disorders." (PMID 37958729, 2023).
diphtheria (1 paper, 2016). A Gram-positive bacterial infection caused by Corynebacterium diphtheriae. "Similarly, SGZ-NSCs that generate almost exclusively projection neurons could be programmed to generate OLs and contribute to remyelination following diphtheria toxin-mediated demyelination in the hippocampus following overexpression of either Ascl1/Mash1 or Olig2 in these cells." (PMID 27854261, 2016).
gastric cancer (1 paper, 2024). A primary or metastatic malignant neoplasm involving the stomach. "ASCL1 expression levels have been considered characteristic of gastric cancer, and ASCL1 overexpression was identified as a signature of gastric tumor." (PMID 38968283, 2024). "ASCL1 was identified as a differentially expressed gene in most gastric cancer subtypes." (PMID 38968283, 2024).
Hirschsprung disease (1 paper, 2022). Hirschsprung disease (HSCR) is a congenital intestinal motility disorder that is characterized by signs of intestinal obstruction due to the presence of an aganglionic segment of variable extent in the terminal part of the colon. "Impaired heterodimer formation with HLH transcription factor ASCL1 and therefore impaired interaction with the ASCL1‐Phox‐Ret pathway was previously discussed to possibly underlie the autonomic dysregulation in PTHS in terms of breathing anomalies and constipation or Hirschsprung disease." (PMID 35908153, 2022).
Hypoglycemia (1 paper, 2022). A decreased concentration of glucose in the blood. "This suggests that high expression of GRP78 and ASCL1, by hypoglycemia and decreased fatty acid synthesis, respectively, may also occur in (Tg/+) fish." (PMID 35469048, 2022).
lung carcinoid tumor (1 paper, 2019). A neuroendocrine neoplasm that arises from the lung. "Considering ASCL1 had been proved to be a lineage-specific oncogene in high-grade neuroendocrine lung cancer and high expression of ONECUT2 in lung carcinoid tumor, we believed that ONECUT2 was unlikely a driver oncogene in lung tumor with neuroendocrine differentiation." (PMID 31882655, 2019).
memory impairment (1 paper, 2023). "This suggests that ASCL1 dysfunction in GABAergic neurons may lead to memory impairment, which is a cognitive symptom observed in SZ patients." (PMID 37958729, 2023).
mental retardation (1 paper, 2013). "In addition to ASCL1 and NEUROG2, other neurodevelopmental transcriptional regulators such as, MEF2C (syndromic mental retardation) and ZEB2 (MWS) were also differentially expressed in TCF4-depleted cells." (PMID 24058414, 2013).
NUT carcinomas (1 paper, 2024). "ASCL1, which is also considered a useful marker for pulmonary small cell carcinoma, was negative in the NUT carcinomas." (PMID 38326851, 2024).
Obesity (1 paper, 2019). Accumulation of substantial excess body fat. "In this study, IPA eased the identification of obesity markers, and we chose ASCL1, HADH, and UCHL1 for validation based on both our proteomic analysis and previous research." (PMID 31929791, 2019).
osteoporosis (1 paper, 2023). A condition of reduced bone mass, with decreased cortical thickness and a decrease in the number and size of the trabeculae of cancellous bone (but normal chemical composition), resulting in increased fracture incidence. "This study provides evidence that elucidates the potential regulatory mechanisms of ASCL1 in the development of osteogenic differentiation in vitro and establishes a theoretical basis for improving osteoporosis." (PMID 37783914, 2023).
osteosarcoma (1 paper, 2022). A usually aggressive malignant bone-forming mesenchymal neoplasm, predominantly affecting adolescents and young adults.
ovarian carcinoma (1 paper, 2021). A malignant neoplasm originating from the surface ovarian epithelium. "Our analysis suggests/predicts that metformin treatment is associated with ‘inhibition of ovarian cancer’ through the master regulator, ASCL1." (PMID 35052372, 2021). "Overall, the master regulator, ASCL1, is involved in various pathways that can lead to the predicted inhibition of ovarian cancer." (PMID 35052372, 2021). "Causal network analysis revealed novel pathways suggesting predicted inhibition of ovarian cancer through master regulator ASCL1 and dataset genes DCX, SEMA6B, HEY2, and KCNIP2." (PMID 35052372, 2021). "The master regulator, ASCL1, inhibits the activation of YAP1, a transcription factor, that is over-expressed at both mRNA and protein levels in ovarian cancer." (PMID 35052372, 2021).
overnutrition (1 paper, 2024). An imbalanced nutritional status resulting from excessive intake of nutrients. "To investigate how Ascl1 contributes to β-cell dysfunction during metabolic stress, we generated β-cell-specific Ascl1 knockout mice and studied their responses to both excitotoxicity and overnutrition." (PMID 39015185, 2024).
pancreatic endocrine tumours (1 paper, 2009). "ASCL1 target genes in the pancreatic endocrine tumour cell line BON1 were identified by RNA interference and microarray expression analysis." (PMID 19744316, 2009). "This study showed altogether 433 target transcripts (158 annotated genes) in the human pancreatic endocrine tumour cell line BON1 that directly or indirectly were regulated by ASCL1, among them several putative oncogenes and suppressor genes." (PMID 19744316, 2009). "ASCL1 also directly or indirectly regulates expression of several putative oncogenes and tumours suppressor genes in pancreatic endocrine tumour cells that may contribute to the neoplastic process." (PMID 19744316, 2009). "Thus, ASCL1 negatively regulates DKK1 and TPH1 in BON1 pancreatic endocrine tumour cells." (PMID 19744316, 2009).
phenylketonuria (1 paper, 2023). Phenylketonuria (PKU) is the most common inborn error of amino acid metabolism and is characterized by mild to severe mental disability in untreated patients. "In 2001, a case of a 5-year-old girl heterozygous for a large de novo deletion at 12q23 (involving the IGF1, PAH, and ASCL1 genes) was described, resulting in phenylketonuria." (PMID 37958729, 2023).
prolactinomas (1 paper, 2017). "There are also few data describing the Notch system in animal models of prolactinomas, even though several components of the Notch pathway such as NOTCH3, ASCL1 and HES1 are altered in human prolactinomas." (PMID 28915655, 2017).
steatosis (1 paper, 2023). Increased lipid within the cytoplasm of cells. "L-carnitine alleviates steatosis in human NASH partly by reducing acetyl-CoA and ER-associated ASCL1." (PMID 37503004, 2023). "Notably, Triascin C alleviated steatosis in Hmgcs2ΔLiv primary hepatocytes, suggesting that ASCL1 drives steatosis in Hmgcs2ΔLiv mice." (PMID 37503004, 2023).
tumour syndrome (1 paper, 2009). "No relations of ASCL1/DKK1 expression to tumour syndrome, MEN 1, or WHO classification were observed." (PMID 19744316, 2009).
viral infection (1 paper, 2018). "High molecular weight of poly-ubiquitylated forms of Ascl1 were detected with the mock viral infection in the presence of MG132 but poly-ubiquitylated Ascl1 forms were severely reduced when Huwe1 was knocked down." (PMID 29545540, 2018).
tumor (173 papers, 2004 to 2026). "In these cancers, ASCL1 expression is often associated with aggressive tumour phenotypes, making it a potential therapeutic target." (PMID 40527452, 2025). "Previous studies have implicated ASCL1 in the initiation and progression of various cancers, where it promotes tumor cell proliferation, supports cell survival and differentiation, and influences drug sensitivity." (PMID 39963143, 2025). "Given the critical role of the tumor microenvironment in modulating immune responses, ASCL1’s association with various immunomodulatory factors—including cytokines, immunomodulators, MHC molecules, and receptors—was assessed across multiple cancers, including BC." (PMID 39963143, 2025). "Integrative analyses identify DNA methylation-driven gene links based on location (H3K27ac, H3K27me3, promoters, gene bodies) pointing to mechanisms underlying dysregulation of genes involved in tumor lineage (ASCL1, AR) and therapeutic targets (PSMA, DLL3, STEAP1, B7-H3)." (PMID 40593552, 2025). "ASH1 expression levels are inversely associated with the degree of tumor differentiation (high-grade tumors show increased expression of this protein), which correlates well with studies indicating that the expression of ASCL1 appears to be restricted to immature cells." (PMID 38315310, 2024). "Ascl1 loss in established NEPC results in transient tumor regression followed by recurrence; however, Ascl1 deletion prior to transplantation completely abrogates lineage plasticity, yielding adenocarcinomas with elevated AR expression and marked sensitivity to castration." (PMID 38645223, 2024). "Notably, loss of either ASCL1 or OLIG2 had only modest effects on tumor progression and survival, likely due to redundant functions of these two transcription factors given their extensive shared binding in GBMs." (PMID 39609428, 2024). "ASCL1 and NEUROD1 regulate different genes, but ASCL1 is the leading cause of tumour formation." (PMID 37870696, 2023). "ASCL1 has also been implicated as an oncogene or tumour suppressor in multiple cancers." (PMID 35366798, 2022). "In one patient presenting with an apparently successful R0 margin, the persistence of ASCL1 methylation preceded tumor recurrence by 4 months." (PMID 40567599, 2025). "Biologically, ASCL1 plays a crucial role in tumor initiation and maintenance by regulating MYCL, SOX2, RET, BCL2, and DLL3, all of which contribute to NE differentiation and tumor survival." (PMID 40333678, 2025). "Given that M2 macrophages are known to promote tumor progression and suppress immune function in malignancies, these results indicate a potential role for ASCL1 in immune evasion." (PMID 39963143, 2025). "By dynamically altering cell states, inducing treatment escape‐associated TFs (such as SOX2, ASCL1), and activating pathways like PI3K/AKT and MYC, the tumour further enhances its ability to adapt to immune attack and metabolic stress." (PMID 40847555, 2025). "Together, these results suggest that lineage-specific TFs are largely expressed in clinical SCLC specimens in a mutually exclusive manner at the tumor level, whereas this principle applies more at the cellular level for ASCL1 and NEUROD1 expression." (PMID 40082639, 2025). "Gene expression profiling on tumor tissue was previously performed in 15 (47%) patients: ten harbored an inflamed (triple negative, I), three an ASCL1+ (A) and two a neuroendocrine (NEUROD1+, N) molecular profile, as previously reported." (PMID 40537796, 2025). "This study aims to systematically evaluate the multifaceted role of ASCL1 in BC, focusing on its influence on biological processes, tumor immunology, treatment response, and prognosis, using a combination of bioinformatics, in vitro, and in vivo methodologies." (PMID 39963143, 2025).